CRP (C-reactive protein)
Diseases named in the same sentence as CRP in open-access papers (continued):
Sharing a sentence is not in itself a finding about the gene and the disease.
breast cancer (continued). "Breast cancer or hernia presented with shorter hospital stays, and patients with pancreatobiliary-related disease (elevated bilirubin) and C reactive protein levels required a longer time to discharge." (PMID 37955965, 2023). "The CRP, CAR, LCR, LHR, and TG/HDL-c were associated with poor survival in women with breast cancer." (PMID 36922570, 2023). "We found that elevated systemic inflammatory markers (CRP, CAR, and LCR) were all significantly associated with reduced OS in breast cancer patients." (PMID 36922570, 2023). "•Higher serum CRP, testosterone, and IGF-1 levels were associated with both the elevated breast cancer risk and mortality." (PMID 38000092, 2023). "The association of CRP and LDH with other biomarkers have a high sensitivity in the detection of metastatic human breast cancer." (PMID 36938312, 2023). "In human breast cancer, the assessment of CA 15-3, CRP, and LDH has been well described and correlated with prognostic factors and overall survival of patients." (PMID 36938312, 2023). "A previous study among breast cancer survivors also found that those who were obese with body fat ≥35% had significantly higher levels of inflammatory markers of C-reactive protein and serum amyloid A protein than their counterparts with body fat <35%." (PMID 38242100, 2023). "In addition, a high pretreatment RDW in patients with breast cancer was associated with poor overall and disease-free survival, along with a large tumor size, a high rate of lymph node metastases, tumor stage, advanced stage, a higher lymphocyte count, and high fibrinogen and CRP levels." (PMID 37174944, 2023). "In conclusion, our data showed that higher CRP, CAR, LCR, LHR, and TG/ HDL-c were associated with increased risk in women with breast cancer." (PMID 36922570, 2023). "The survival curves of CRP, CAR, and LCR in women with breast cancer showed that patients with high CRP, high CAR, or high LCR had a worse prognosis than patients with low CRP(P = 0.0025), low CAR (P < 0.001), or low LCR (P < 0.001), respectively." (PMID 36922570, 2023). "IL-6 was also correlated with elevated CRP in different kinds of cancers including breast cancer, renal cancer, lung cancer, and colorectal cancer." (PMID 35924148, 2022). "Physical activity has been shown to reduce levels of pro-inflammatory biomarkers, and there have been studies that reveal lower levels of CRP in physical active breast cancer survivors." (PMID 36497878, 2022). "Lastly, bidirectional MR did not provide evidence for reverse causality between schizophrenia, breast cancer, prostate cancer and COPD (as exposures) and CRP levels (as outcome)." (PMID 35459240, 2022). "In accordance with the present study, CRP was moderately-severely elevated (5.1 ± 5.3 mg/dL) in 91% of overweight breast cancer survivors (n = 42) who were using adjuvant hormone therapy." (PMID 35241143, 2022). "An increased DAL was also significantly associated with increased plasma C-reactive protein (CRP) and hemoglobin A1c (HbA1c) levels, and reduced overall physical health in breast cancer survivors." (PMID 35505426, 2022). "It has been reported that elevated levels of inflammation-related markers CRP, TNF, IL-6, and IL-8 are associated with poor prognosis in breast cancer patients." (PMID 36467500, 2022). "For example, breast cancer survivors with better postdiagnosis diet quality showed lower CRP levels (1.6 mg/L vs. 2.5 mg/L) and higher scores on the Healthy Eating Index (2005)." (PMID 35160104, 2022). "For example, research in breast cancer patients show that apart from lowering blood pressure levels, exercise lowers the inflammatory marker C-reactive protein, suggesting an anti-inflammatory effect of exercise." (PMID 35882678, 2022). "Prior studies have indicated that elevated C-reactive protein (CRP) and serum amyloid A (SAA) are associated with an increased risk of breast cancer recurrence." (PMID 35136076, 2022).
breast cancer (continued). "The respective median CRP values for the breast cancer and control groups were 1.95 (0.62 - 4.58) and 1.38 (0.62-4.23) μg/mL, respectively, which were not significantly different." (PMID 35677046, 2022). "We found strong associations of CRP DNA methylation risk score to lung function (FEV1, FVC) as well as COPD and receipt of chemotherapy among breast cancer patients." (PMID 35504910, 2022). "Clinicopathological characteristics of breast cancers according to neutrophil-to-lymphocyte ratio (NLR) or c-reactive protein/albumin ratio (CAR) levels." (PMID 35317078, 2022). "Eight breast cancer patients had CRP values of ≥ 10 μg/mL (range 11.6 - 22.0 μg/mL) and one in the control group (16.1 μg/mL)." (PMID 35677046, 2022). "CRP levels were relatively low in breast cancer patients compared to those in patients with other cancers." (PMID 35752767, 2022). "This study was determined to evaluate the prognostic value of neutrophil-to-lymphocyte ratio (NLR) and C-reactive protein/albumin ratio (CAR) prior to surgery in luminal breast cancers (BC) with HER2-negativity." (PMID 35317078, 2022). "CRP is reported to bind to integrin α2 and Fcγ receptor I, leading to the progression of breast cancer." (PMID 33801202, 2021). "Recently, serum CRP level has been shown to be closely related to the prognosis of a variety of malignant tumors, including breast cancer, colorectal cancer, and thymic epithelial tumors." (PMID 33270989, 2021). "A lower serum CRP level in patients with IGM compared to patients with breast cancer (median: 0.15 vs. 0.56 mg/dL; p < 0.001) was reported in a previous study." (PMID 34066203, 2021). "High levels of CRP and SAA, the multiplicative interaction, CRP*SAA, and high-grade pathology were all significantly associated with increased risk of relapsed breast cancer." (PMID 33483516, 2021). "Previous studies show that breast cancer survivors have high CRP levels immediately after treatment, but they tend to normalize with the passage of time." (PMID 34436041, 2021). "It was found that the most increasing parameters of breast cancer risk were high levels of NF-κB, TNF-α, IL-6, PCT, PTX-3, and CRP." (PMID 33776564, 2021). "CRP has been identified in nipple aspirate fluid (NAF) of healthy women and has been positively related to breast cancer risk as predicted by the Gail model." (PMID 34359821, 2021). "In the present study, it was found that both hs-CRP levels and Apo-B markers were significantly elevated in breast cancer patients at the time of diagnosis, in comparison with healthy controls with a preference for hs-CRP over Apo-B." (PMID 34711013, 2021). "(A) Indirect studies include those demonstrating inflammatory changes which are reflected in plasma biomarkers such as C-reactive protein (CRP), and studies examining the effect of anti-inflammatory agents such as aspirin on risk for breast cancer." (PMID 34359821, 2021). "In patients with breast cancer, serum CRP level is higher in the elderly compared to the younger group." (PMID 34066203, 2021). "In summary, these results demonstrate that levels of serum inflammatory proteins CRP and SAA are independently associated with an increased risk of breast cancer relapse in HR+/HER2− breast cancer." (PMID 33483516, 2021). "Several previous studies reported findings linking elevated preoperative CRP levels to increased lymph node metastasis and limited OS in breast cancer patients." (PMID 33562331, 2021). "C-reactive protein, measured before and after treatment, was investigated through a retrospective study on 366 women affected by breast cancer for its possible role as a pain predictor for potential different responders by ethnicity to radiotherapy." (PMID 34685397, 2021). "Only one inflammatory marker, C-reactive protein (CRP), a sensitive and widely used systemic marker for inflammation, has been extensively studied and shown to be correlated with breast cancer risk." (PMID 33435254, 2021).
breast cancer (continued). "Increased serum CRP levels were also correlated with the progression of different types of malignancies including breast cancer." (PMID 34711013, 2021). "Our finding of the SALL1 SNP’s association with CRP at the GWA level and with breast cancer risk is supported by these previous biologic studies and further suggests the involvement of SALL1 in immune mechanisms of breast cancer tumorigenesis." (PMID 33441805, 2021). "Elevated markers of inflammation such as C-reactive protein (CRP), IL-6 and TNFA are associated with an increased risk of breast cancer, increased risk of recurrence, and reduced tumour free survival." (PMID 34771552, 2021). "The clinical value of serum CRP has also been explored in tumor settings, such as ovarian cancer, breast cancer, colorectal cancer, lung cancer, prostate cancer, renal cell carcinoma, and pancreatic cancer." (PMID 35070979, 2021). "CRP is increased in many cancers, including lymphoma, lung cancer, pancreatic cancer, esophageal cancer, gastric cancer, breast cancer, prostate cancer, and kidney cancer." (PMID 32309219, 2020). "In conclusion, we have shown that low levels of NLR and CRP are significantly associated with improved PFS and OS in advanced breast cancer treated with bevacizumab plus paclitaxel." (PMID 32002126, 2020). "Cancer-related inflammation is one of the hallmarks of cancer, and interleukin-1 (IL-1), IL-6, tumor necrosis factor alpha (TNF-α), and C-reactive protein (CRP) are widely recognized as biomarkers of systemic inflammation related to breast cancer." (PMID 33108715, 2020). "Moderate exercise can reduce the expression of mRNA levels of TNF-α, IL-6, IL-18, and CRP in the livers of breast cancer mice." (PMID 32309219, 2020). "The prognostic role of CRP serum levels has been shown for a variety of different malignancies such as glioblastoma, breast cancer and ovarian cancer." (PMID 32604773, 2020). "CRP levels were significantly increased in the breast cancer group (BC: 4.39 ± 0.53) compared to the normal control group (CTL: 1.00 ± 0.11, P < 0.001)." (PMID 32309219, 2020). "In obese postmenopausal women, there is a positive correlation between circulating C-reactive protein (CRP)—a marker of inflammation—and breast cancer risk." (PMID 32630445, 2020). "The results show that long-term exercise reduces CRP mRNA expression in breast cancer mice, and long-term running can inhibit CRP in the liver." (PMID 32309219, 2020). "The Health Aging and Body Composition study of women aged 70–79 years old evaluated baseline inflammatory markers (e.g., IL6, TNFRα, CRP) and incident breast cancer events." (PMID 33004039, 2020). "Findings for adiponectin, PAI‐1 and CRP in sensitivity analyses using cis‐SNP instruments for both overall and oestrogen receptor‐stratified breast cancer were consistent with those from the primary analysis." (PMID 32134113, 2020). "This is the first study to demonstrate the predictive utility of NLR and CRP for bevacizumab plus paclitaxel therapy in breast cancer to the best of our knowledge." (PMID 32002126, 2020). "The combination of ruxolitinib and capecitabine in breast cancer patients with elevated CRP was also investigated in a Phase II clinical trial (NCT02120417)." (PMID 33521321, 2020). "Second, considering the involvement of CRP in fatigue and prognosis of breast cancer, future follow-up studies will focus on monitoring CRP levels, QOL, and clinical outcomes." (PMID 31138314, 2019). "In previous studies, patients with higher CRP levels at the time of the breast cancer diagnosis had increased breast cancer recurrence and a reduction in both overall and disease-free survival time." (PMID 31443226, 2019). "We have already demonstrated elevated levels of inflammatory markers, such as C-reactive protein and platelet to lymphocyte ratio to be related to poorer survival among breast cancer patients." (PMID 30816333, 2019).
breast cancer (continued). "Higher concentrations of many inflammatory markers, including CRP, IL-1β, IL-6, and TNF-a, have been linked with a higher risk of breast cancer through the stimulation of angiogenesis, proliferation, migration, metastasis, and prevention of apoptosis." (PMID 31430979, 2019). "Clinically, a positive association between circulating levels of C-reactive protein (CRP), a well-known marker of active inflammation, and postmenopausal breast cancer risk was found among women with excess adiposity." (PMID 30634494, 2019). "Elevated inflammatory markers such as CRP, neutrophil to lymphocyte ratio, interleukin-6, have been related to poorer survival amongst breast cancer patients." (PMID 31262969, 2019). "In women diagnosed with primary breast cancer recruited to the HEAL (Health, Eating, Activity, and Lifestyle) study, serum levels of the inflammatory biomarkers amyloid A and CRP were associated with reduced disease-free survival." (PMID 30634494, 2019). "This is the first pilot study of CRP in RT-related pain, particularly in obese breast cancer patients." (PMID 31138314, 2019). "Breast cancer survivors who adopted higher quality diets post-diagnosis exhibited lower C-reactive protein (CRP) levels, compared to those with lower quality diets." (PMID 31652816, 2019). "C-reactive protein (CRP) is already a developed serum biomarker for metastasis of various cancers including advanced stages of breast cancer." (PMID 29344009, 2018). "Inflammatory markers such as C-reactive protein in esophageal squamous cancer, Colony-stimulating factor-1 in mammary tumor, and inhibitors of metalloproteinases in NSCLC, all have been suggested as alternative markers for tumor progression." (PMID 30348119, 2018). "Endogenously produced and extracellular S1P upregulated expression of C-reactive proteins (CRP) in breast carcinoma cells." (PMID 29385066, 2018). "In our study, the placebo group showed an increase in CRP levels, suggestive of an inflammatory response to the tumor, while, in n-3 fatty acids treated-breast cancer patients, the CRP showed a more regulated response." (PMID 29061183, 2017). "CRP increased in cancer including breast cancer, it is a prognostic indicator, and its increased levels indicate more aggressive disease, higher risk of recurrence and reduced survival." (PMID 28657165, 2017). "Cumulatively, more than 50% of these patients with all tumor types, except breast cancer, had CRP levels greater than the upper normal limit." (PMID 29108370, 2017). "This notion is underscored by the observation of Dooley and colleagues who noted a positive association between C-reactive protein levels and cognitive depressive symptoms among BDNF Met carriers of breast cancer survivors." (PMID 28056856, 2017). "Consistent with previous studies of colorectal, esophageal, and hepatic carcinomas, an elevated serum CRP concentration is an indicator of unfavorable prognosis in patients with breast carcinoma." (PMID 28489884, 2017). "Both preoperative CRP and PLR values were independently associated with poor prognosis in patients with breast carcinoma; these were superior to other inflammation-based scores in terms of prognostic ability." (PMID 28489884, 2017). "A NLR greater than or equal to 2.1 was associated with increased T stage, TNM stage, relapse events, higher CRP value, and breast cancer specific mortality." (PMID 27198767, 2016). "Ravishankaran and Karunanithi determined preoperative levels of serum IL-6 and CRP in breast cancer to correlate them with the stage of the disease and prognosis." (PMID 26693355, 2015). "CRP lowering agents along with chemotherapeutic drugs will improve the survival of breast cancer patients." (PMID 26693355, 2015). "Recently HEAL study commented reduced levels of CRP in 741 breast cancer survivors treated with tamoxifen." (PMID 26693355, 2015). "Combined OR per natural unit change in CRP for breast cancer was 1.16 (95% CI: 1.06–1.27) with moderate heterogeneity." (PMID 26693355, 2015).
breast cancer (continued). "Overall analysis of this meta-analysis reported that a natural log unit rise in CRP level results in 16% increase in breast cancer condition." (PMID 26693355, 2015). "In this study we compared few serum elements (Calcium (Ca), Phosphorus (P), Magnesium (Mg), Zinc (Zn) and high sensitive-CRP) in patients with benign and malignant breast tumor to find any related prognostic and predictive value." (PMID 26865928, 2015). "Associations between elevated C-reactive protein (CRP) and breast cancer risk have been reported for many years, but the results remain controversial." (PMID 26001129, 2015). "Patient-reported arthralgia and co-morbid fatigue and insomnia were associated with elevated CRP, eotaxin, MCP-1, and VDBP among a group of breast cancer survivors taking AIs." (PMID 26126656, 2015). "Numerous epidemiological prospective studies proved CRP as a well-established independent prognostic marker in breast cancer." (PMID 26693355, 2015). "Consistent with this evidence, data from epidemiologic cohorts of women have shown that elevated C-reactive protein (CRP), a biomarker of systemic inflammation, is associated with breast cancer risk." (PMID 26305095, 2015). "To explore the heterogeneity among studies of one unit change in ln(CRP) and breast cancer, we performed subgroup analyses." (PMID 26001129, 2015). "So predictive ability for the outcome of the patients with breast cancer can be improved with the addition of CRP to other prognostic factors." (PMID 26693355, 2015). "Only few studies have examined the impact of pre-operative CRP levels on breast cancer prognosis, thus far with mixed results." (PMID 25340395, 2014). "GPS is based on a combination of CRP and albumin and has been evaluated in a variety of cancers, such as renal cancer, breast cancer, non-small cell lung cancer, gastroesophageal cancer, pancreatic cancer, and colorectal cancer." (PMID 24885814, 2014). "A recent meta-analysis underscored that CRP, as a biomarker of inflammation, is related to impaired outcome also in breast cancer patients." (PMID 25340395, 2014). "The correlations between serum CRP and gene expression levels in the corresponding carcinoma of the breast were assessed using Spearman's rank correlation, controlled for false-discovery rate." (PMID 25340395, 2014). "These values are comparable to those reported by Thomson and colleagues who described a mean high sensitivity CRP of 5.1 (5.3) mg.L-1 in an overweight cohort of breast cancer survivors." (PMID 23855321, 2013). "Results identify that the insulin resistant group displayed alterations in both measures of insulin-glucose homeostasis and CRP, two significant predictors of breast cancer outcome." (PMID 23855321, 2013). "We have previously demonstrated in our cross-sectional study that inflammatory biomarkers known to be elevated in breast cancer patients (IL-6 and CRP) are also increased in obese and insulin resistant pre-menopausal women." (PMID 23374911, 2013). "In order to examine the predictive value of inflammatory biomarkers in breast cancer patients, we measured serum ferritin and CRP in HER2/neu-overexpressing patients before undergoing trastuzumab-containing therapy." (PMID 23300545, 2012). "The largest of these studies (N = 162) and with the strongest methodology did show significant improvements in QOL, fatigue, mood, and CRP levels, but only 34% of the participants in this study had breast cancer." (PMID 22997532, 2012). "Elevated circulating levels of CRP and SAA have been associated with greater probability of breast cancer death and with more advanced disease stage at diagnosis." (PMID 22873489, 2012). "In summary, this study demonstrates that elevation in the inflammatory biomarkers serum ferritin and CRP is a common phenomenon in advanced breast cancer patients and is predictive of response to trastuzumab-containing therapy." (PMID 23300545, 2012).